IL18 (interleukin 18)
Diseases named in the same sentence as IL18 in open-access papers (continued):
Sharing a sentence is not in itself a finding about the gene and the disease.
hepatocellular carcinoma (34 papers, 2008 to 2025). A malignant tumor that arises from hepatocytes. "Further, IL-18 polymorphism has been linked to an increased or decreased progression of hepatocellular carcinoma." (PMID 37372463, 2023). "Cytokines produced by these resident as well as infiltrating macrophages such as TNFα, transforming growth factor β (TGF-β), interleukin 6 (IL-6) and 18 (IL-18) are highly associated with the development and progression of hepatocellular carcinoma (HCC)." (PMID 36276076, 2022). "This study meta-analyzed the literature on possible association of polymorphisms -137 (rs187238) and -607 (rs1946518) in the interleukin-18 (IL-18) promoter with risk of hepatocellular carcinoma (HCC)." (PMID 28000712, 2016). "Lower levels of caspase-1, IL-1β, and IL-18 were observed in hepatocellular carcinoma (HCC) tissues compared with adjacent normal ones, implying the role of pyroptosis in tumorigenicity." (PMID 35432318, 2022). "At the same time, they observed that IL-18 promoted hepatoma cell metastasis and migration, revealing the dual effects of IL-18." (PMID 33015196, 2020). "In hepatocellular carcinoma cells, hypoxia induces caspase-1 activation, cleavage and release of proinflammatory cytokines, IL-1β and IL-18." (PMID 29184853, 2017). "Associations between polymorphisms in vitamin D receptor (VDR)/vascular endothelial growth factor (VEGF)/interleukin-18 (IL-18)/mannose-binding lectin (MBL) and susceptibility to hepatocellular carcinoma (HCC) were already explored by many studies, yet the results of these studies were inconsistent." (PMID 31830994, 2019). "IL-12, IL-15, and IL-18 have demonstrated the ability to activate NK cells against hepatocellular carcinoma (HCC), melanoma, and breast cancer." (PMID 37484408, 2023). "In turn, elevated IL-18 can inhibit HBV replication in murine and hepatoma cell lines through induction of IFN-γ and other unrevealed mechanisms." (PMID 35854256, 2022). "Pyroptotic macrophages can increase the cytotoxicity of NK cells in hepatocellular carcinoma by producing CCL5 and IL-18 and thus kill more tumor cells." (PMID 35656090, 2022). "For example, sorafenib could motivate the cytotoxicity of natural killer cells (NKs) to hepatocellular carcinoma (HCC) cells by inducing the pyroptotic cell death in macrophages, and this effect was significantly related to the secretion of IL-18 and IL-1β." (PMID 35873495, 2022). "For example, miR-20a-5p was downregulated during liver fibrosis and transfection of miR-20a-5p reduced the production of the proinflammatory cytokines IL-6, TNF-α, IL-18, and IFN-γ in a murine hepatoma cell line by targeting transforming growth factor beta 2 (TGFB2)." (PMID 36634655, 2023). "In addition, IL‐18 was reported to be capable of stimulating the invasion and metastasis of PDAC and hepatic carcinoma." (PMID 32347623, 2020). "Although these patients do not formally have hepatocellular carcinoma, they represent a patient population at risk for developing liver cancer and may be viewed as pre-cancerous, which might be the reason for the elevated IL-18 levels in the untreated cirrhotic patients." (PMID 19325795, 2008). "In contrast, primary hepatocytes (the target cells of HCV infection) and hepatoma cell lines failed to produce IL-18 when cultured with this panel of HCV pre-infection and V plasma samples or with HCVJFH-1 despite productive HCVJFH-1 infection of Huh 7.5 and 7.5.1 cells." (PMID 24788318, 2014). "However, studies focused on its involvement in hepatocellular carcinoma (HCC) remains controversial, and no much study has taken IL-18 serum levels into consideration." (PMID 26213495, 2015).
adult-onset Still disease (33 papers, 2006 to 2026). A rare inflammatory multisystem disorder characterized clinically by fever of unknown origin, arthralgia or arthritis, hyperleucocytosis, and typical skin rash. "Elevated circulating levels of IL-18 have been observed in patients with systemic juvenile idiopathic arthritis (sJIA) and adult-onset Still’s disease (AOSD), two conditions associated with dysregulated innate immune responses." (PMID 37415987, 2023). "Interleukin (IL)-18 is markedly elevated in systemic inflammatory diseases that cause the ‘cytokine storm’ such as adult-onset Still’s disease (AOSD) and hemophagocytic lymphohistiocytosis (HLH)." (PMID 34691064, 2021). "Recently, we reported that genetic polymorphisms within the human IL18 gene were associated with disease susceptibility to adult-onset Still's disease (AOSD), which is characterized by extraordinarily high serum levels of IL-18." (PMID 16563174, 2006). "In addition, circulating IL-18 has been linked to dyskeratosis and cell death in rashes associated with adult-onset Still’s disease." (PMID 32644977, 2020). "Serum interleukin-18 level may be a good diagnostic biomarker to monitor adult onset Still’s disease activity in older patients, measuring levels in both the acute and convalescent phases." (PMID 29986752, 2018). "The potential efficacy of IL-18 blockade in adult-onset Still disease and of IL-33 blockade in AD are being assessed in clinical trials." (PMID 36012744, 2022). "A recently published phase II trial of an IL-18 binding protein (IL-18 bp) drug to treat adult-onset Still’s disease demonstrated a favourable efficacy safety profile." (PMID 31276585, 2019). "sJIA and its adult form, adult-onset Still's disease (AOSD), share common pathophysiological mechanisms: they have been shown to associate with raised serum levels of IL-1, IL-6, and IL-18." (PMID 30406861, 2018). "We report a case of adult onset Still’s disease in an older patient successfully treated with steroids in which interleukin-18 was a useful marker of disease activity." (PMID 29986752, 2018). "It is noteworthy that serum levels of IL-18 in patients with adult-onset Still's disease were greatly increased compared to control subjects as previously reported." (PMID 21435242, 2011). "The level of IL-18 is reportedly increased in both the serum and rheumatoid synovial fluid, as well as in the bone marrow, of patients with RA, juvenile RA, adult-onset Still's disease and psoriatic arthritis." (PMID 21435242, 2011). "Among other cytokines, IL-18 is thought to play a pivotal role in the inflammatory cascade in patients with adult-onset Still disease by orchestrating the Th1 response and inducing other cytokines, such as IL-1β, IL-8, tumor necrosis factor-α TNF-α and IFN-γ." (PMID 20565717, 2010). "However, patients with sJIA and adult-onset Still’s disease (AOSD) show extremely elevated levels of IL-18." (PMID 35778759, 2022). "High levels of IL-18 have been found in neonates born to a mother with adult onset Stills disease." (PMID 33568193, 2021). "In addition, Kasama and colleagues reported that gene expression levels of Cx3cl1 and Il-18 are positively correlated with each other in adult-onset Still’s disease." (PMID 32941527, 2020). "Moreover, systemic juvenile idiopathic arthritis or adult-onset Still’s disease are also characterized by high serum IL-18 concentrations and are treated by IL-18BP (binding protein).." (PMID 32297262, 2020). "Adult-onset Still’s disease is a multi-systemic inflammatory disease characterized by upregulated IL-18 levels and downregulated IL-18BP in the circulation, mediated by an unknown mechanism." (PMID 30717382, 2019). "The serum levels of IL-18 in 67 healthy controls, 145 patients with RA, 6 patients with adult-onset Still's disease, 31 patients with OA and 39 patients with SLE were 159.9 ± 10.9, 299.4 ± 16.1, 6,566.1 ± 2,679.7, 195.5 ± 12.8 and 372.3 ± 32.6 pg/mL, respectively." (PMID 21435242, 2011).
adult-onset Still disease (continued). "Therefore, elevated miR-134 in adult-onset Still’s disease might induce the upregulation of IL-18 by inhibiting IL18BP, and therefore, miR-134 might be a potential biomarker for this disease." (PMID 30717382, 2019). "In addition to NLRC4-MAS, IL-18 is associated with various severe chronic inflammatory diseases such as CAPS, familial Mediterranean fever, adult-onset Still’s disease (AOSD), pyogenic arthritis, pyoderma gangrenosum, acne syndrome, and systemic juvenile idiopathic arthritis with MAS18–22." (PMID 30992532, 2019). "Adult-onset Still’s disease (AOSD) is a self-inflammatory disease showing macrophage and neutrophil activation by inflammatory cytokines such as TNF-α, IL-6, and IL-18." (PMID 33627085, 2021). "Adult-onset Still’s disease (AOSD) is a self-inflammatory disease exhibiting macrophage and neutrophil activation by inflammatory cytokines such as tumor necrosis factor-α (TNF-α), interleukin-6 (IL-6), and interleukin-18 (IL-18)." (PMID 33627085, 2021).
Autoimmunity (33 papers, 2010 to 2026). The occurrence of an immune reaction against the organism's own cells or tissues. "In long COVID, IL-18 is linked to neuroinflammation and autoimmunity, potentially driving fatigue and cognitive symptoms (“brain fog”)." (PMID 40943354, 2025). "IL-1β and IL-18, members of the IL-1 superfamily of cytokines, promote processes associated with infection, inflammation, and autoimmunity." (PMID 37762434, 2023). "Inflammasomes, which mediate maturation of interleukin-1β (IL-β) and interleukin-18 (IL-18) and lead to pyroptosis, have been linked to various autoimmune disorders." (PMID 29915579, 2018). "Reduced quantities of NK cells have been associated with increased IL-18 levels in HIV as well as in autoimmunity." (PMID 28900426, 2017). "For example, autoimmune conditions often require azathioprine, leflunomide, or T/B cell blockade, while autoinflammation can be managed with colchicine or cytokine (IL-1β, IL-18, IL-36) inhibitors." (PMID 41550415, 2026). "Although there is less evidence of IL‐18 as a key driver of disease pathology, increased IL‐18 production has been demonstrated in both experimental models and patients with autoimmune conditions." (PMID 40686254, 2025). "Interleukin-18 (IL-18) is a potent pro-inflammatory cytokine that is involved in various innate and adaptive immune processes related to infection, inflammation, and autoimmunity." (PMID 37446301, 2023). "Review: Interleukin-18 (IL-18) is a proinflammatory cytokine that promotes various innate immune processes related to infection, inflammation, and autoimmunity." (PMID 35958573, 2022). "IL-18 is one of the factors most related to autoimmunity due to its potent and complex pro-inflammatory action." (PMID 35205739, 2022). "Several factors that play important roles in autoimmunity are present in TA and CD, such as lymphocyte subtype and proinflammatory cytokines (IFNγ, TNFα, IL-6, IL-17, IL-18)." (PMID 33628228, 2021). "IL-18 was shown to promote autoimmunity by stimulating innate IL-17 production by T cells, and the increased levels of serum IL-18 in patients with MS illustrate its key role in the pathogenesis of MS." (PMID 29849483, 2018). "Further highly upregulated proteins, IL18 and sulfotransferase 1A1, were already reported in autoimmunity." (PMID 29026368, 2017). "Rac-1 is directly implicated in the activation of caspase-1, which is crucial for processing and secretion of the proinflammatory cytokines IL-1β and IL-18, promoting autoimmunity." (PMID 24147031, 2013). "Therapeutic strategies targeting IL-18 in autoimmunity include IL-18 inhibition, IL-18BP, soluble IL-18 receptor, and monoclonal antibodies." (PMID 27713252, 2010). "IL-18 induces inflammatory and cytotoxic immune cell activities, contributing to autoimmunity." (PMID 40305201, 2025). "IL-18 is highly involved in host immune response as well as autoimmunity." (PMID 39451257, 2024). "IL-18 could potentially induce inflammatory and cytotoxic immune cell activities leading to autoimmunity." (PMID 36032110, 2022). "Therefore, in order to gain more insight into the place of IL-BP and other drugs targeting IL-18 for the treatment and control of autoimmune conditions, additional research is required." (PMID 36032110, 2022). "Furthermore, the moloc analyses suggested that innate immune cells such as monocytes and neutrophils are likely to drive this association, supporting the current dogma that innate production of IL-18 stimulates Th1/Th17-mediated autoimmunity in IBD." (PMID 31276585, 2019). "Thus, the upregulation of proinflammatory cytokines IL-1 and IL-18 during the long-term HDBR and the slower resolving after the experiment suggest that prolonged microgravity could pose a potential risk in autoimmunity and inflammation." (PMID 24143230, 2013). "IL-18 is identified as a potential biomarker for active SLE, whereas blocking IL-18 was found to delay the onset of SLE-like autoimmunity." (PMID 40791585, 2025).
Autoimmunity (continued). "Th1 cells and related transcription factor T-bet and inflammatory cytokines including IFNγ, TNFα, IL-2, IL-18, TGF-β, and IL-12 are important in inflammatory responses such as autoimmunity development." (PMID 38164134, 2023). "The Th1 cell family including Th1 cells, transcription factor T-bet, and related cytokines IFNγ, TNFα, IL-2, IL-18, TGF-β, and IL-12 have been widely discussed in autoimmunity, such as SLE." (PMID 38164134, 2023). "It is worth noting that in the present study serum IL-6, IL-12, and IL-18 levels were found elevated not only in the GD but also in the TNG group, in which autoimmunity was not involved in the pathologic process." (PMID 24367378, 2013).
glioma (33 papers, 2010 to 2025). A benign or malignant brain and spinal cord tumor that arises from glial cells (astrocytes, oligodendrocytes, ependymal cells). "So we also substantiated a crucially positive correlation of the risk score with IL-1α, IL-1β, IL-6, IL-8, and IL-18 expression levels in patients with glioma." (PMID 34114970, 2021). "We first performed clinical data analysis to determine the association of IL-1β and IL-18 expression with clinical and molecular characteristics in gliomas." (PMID 31139563, 2019). "Taken together, these results indicate that increased expression of IL-1β and IL-18 is associated with poor prognostic outcomes for glioma patients." (PMID 31139563, 2019). "Our result indicates that both FN1 and IL-18 are significantly associated with poor prognosis of glioma patients (P-value <0.05)." (PMID 31118022, 2019). "Research has established a strong association between IL-18 expression and glioma progression, particularly within the tumor microenvironment, where it stimulates macrophages and other immune cells to release pro-inflammatory cytokines, thereby promoting tumor cell proliferation and metastasis." (PMID 40656950, 2025). "By elucidating the function of IL-18 and its associated signaling pathways, we aim to contribute to the development of targeted interventions that may improve treatment outcomes for glioma patients." (PMID 40656950, 2025). "In the glioma microenvironment, overexpression of IL-18 often leads to enhanced local inflammation, which promotes tumor cell proliferation and invasive behavior." (PMID 40656950, 2025). "We focus on the expression profiles of IL-18 signaling-related genes (ISRGs) and their functional implications in glioma." (PMID 40656950, 2025). "Specifically, microglia in the glioma microenvironment become activated and produce IL-18, which in turn enhances the migratory capacity of glioma cells." (PMID 40656950, 2025). "The role of IL-18 in glioma is complex and dynamic, significantly influencing tumor biology through multiple mechanisms." (PMID 40656950, 2025). "IL-18 serves not only as a potential prognostic marker for glioma progression but also as a promising therapeutic target due to its role in immune modulation." (PMID 40656950, 2025). "This study investigates the expression levels of PTX3, a key component of the IL-18 signaling pathway, and its implications for the prognosis of glioma patients." (PMID 40656950, 2025). "Simultaneously, we demonstrated that inhibiting p-STAT3 through EZH2 enhances NLRP3 inflammasome activity, promoting glioma pyroptosis and the expression of inflammatory factors IL-1β and IL-18." (PMID 39069522, 2024). "IL‐18 was also shown to elicit anti‐glioma response in vivo through production of IFN‐γ and NO from macrophages and NK cells." (PMID 36161280, 2023). "Considering the results of related studies, glioma, breast, and bladder carcinoma prognosis are responsible for increasing the levels of IL-18 in circulation." (PMID 36742134, 2023). "Recent research also suggests that gliomas derived from extracellular matrix-activated microglia secrete IL-18 to enhance the migration of glioma cells." (PMID 36713560, 2022). "BBR inhibits the inflammatory cytokine caspase-1 activation through ERK1/2 signaling as well as glioma cells’ subsequent development of IL-1 and IL-18." (PMID 34885950, 2021). "In syngeneic mice models, supplementary IL-18 administration suppressed the growth of Meth A sarcoma and mouse glioma cells, suggesting that IL-18 plays an essential role in host mechanisms of defense against tumors." (PMID 30925760, 2019). "Further, IL-1β and IL-18 expression was significantly increased in mesenchymal gliomas than other types of gliomas." (PMID 31139563, 2019). "Immunohistochemical analysis showed that the expression of IL-18 and IL-1β were significantly upregulated in glioma tissues compared to normal brain tissues." (PMID 31139563, 2019).